SENP1 (SUMO specific peptidase 1)
Diseases named in the same sentence as SENP1 in open-access papers (continued):
Sharing a sentence is not in itself a finding about the gene and the disease.
prostate carcinoma (continued). "Moreover, it was shown that SENP1 expression directly correlates with prostate cancer aggressiveness and recurrence." (PMID 27178176, 2016). "All these results show the contribution of SENP1 to the progression of prostate cancer, and suggest that SENP1 may be a prognostic marker and a therapeutic target for metastasis in prostate cancer patients." (PMID 27178176, 2016). "Since Mc interacts with SENP1 and inhibits proliferation in prostate cancer cells, SENP1 inhibition may contribute to the Mc-induced reduction in proliferation." (PMID 27449295, 2016). "SENP1 inhibition reduces the proliferation of prostate cancer cells." (PMID 27449295, 2016). "Two studies analyzing SENP1 in 115 and 150 Asian prostate cancer patients suggested that SENP1 overexpression might be an independent marker of poor prognosis." (PMID 26202067, 2015). "Furthermore, the overexpression of SENP1 has been observed in more than half of the studied samples of prostate cancer and prostatic intraepithelial neoplasia lesions." (PMID 25893082, 2015). "Accumulating evidence indicates that SENP1 is involved in the desumoylation of androgen receptor (AR), and that overexpression of SENP1 increases AR transcriptional activity, which has been found in >50% of high-grade precancerous prostate tissues, and in numerous prostate cancer cases." (PMID 35807394, 2022). "Thus, it was considered that SENP1 may play an important role in momordin Ic-induced cell death in prostate cancer cells, even though the downstream effectors of SENP1 that mediate momordin Ic-induced apoptosis are currently unknown." (PMID 33603816, 2021). "Natural products targeting SENP1 are relatively rare but at least two plant products have been reported: the pentacyclic triterpenoid momordin Ic which directly interacts with SENP1 in prostate cancer cells and the triterpenoid triptolide which down-regulates SENP1 in prostate cancer cells." (PMID 33534099, 2021). "In addition, high expression of SENP1 is found in prostate cancer and thyroid oncocytoma." (PMID 34422639, 2021). "However, the role of SENP1 in regulating deSUMOylation of SMAD4 in prostate cancer is largely unknown." (PMID 28417919, 2017). "Therefore, we investigated if SENP1 deSUMOylated SMAD4 in prostate cancer cells." (PMID 28417919, 2017). "Therefore, SENP1 is a potential target for treatment of advanced prostate cancer." (PMID 28417919, 2017). "However, SENP1, which could reverse the SUMOylation of protein, is significantly up-regulated in prostate cancers." (PMID 28417919, 2017). "Targeting SENP1 may be a novel approach for the treatment of prostate cancer." (PMID 27449295, 2016). "SENP1 and HIF-1α interacts with each other to regulate tumorigenesis through enhancing glycolysis in prostatic carcinoma cells." (PMID 38389923, 2024). "SENP1 is considered to be a promising target for the treatment of hepatocellular carcinoma (HCC) and prostate cancer." (PMID 35807394, 2022). "Like breast or prostate cancers that show elevated SENP1 expression, our tissue microarray (TMA) analysis found that high SENP1 expression combined with high HIF2α expression showed a poor overall survival of ccRCC patients." (PMID 36284084, 2022). "SENP1 expression in PCa patient samples positively correlates with the expression of MMP2 and MMP9 that are frequently overexpressed in prostate cancer." (PMID 34503213, 2021). "SENP1 can regulate MMP-2 and MMP-9 through the HIF1α signaling pathway, thereby promoting the progression of prostate cancer cell lines and bone metastasis." (PMID 33123273, 2020). "In advanced prostate cancer, small ubiquitin-like modifier (SUMO)-specific cysteine protease 1 (SENP1) is up-regulated." (PMID 28417919, 2017). "In this study, we silenced SENP1 in PC3M cells, a prostate cancer cell line with high metastatic potential, and over-expressed SENP1 in LNCaP cells, prostate cancer cells with low metastatic phenotype." (PMID 28417919, 2017).
prostate carcinoma (continued). "We and others report transcriptional induction of the Sentrin/SUMO-specific isopeptidase SENP1 in human pre-cancer lesions or prostatic intraepithelial neoplasia (PIN) and correlative elevation of SENP1 protein with enhanced prostate cancer (PCa) malignancy." (PMID 27852060, 2017). "Thus, SENP1 may play an important role in Mc-induced cell death in prostate cancer cells." (PMID 27449295, 2016). "Prostate cancer cell growth could be induced because hypoxia-inducible factor 1 alpha (HIF-1α) activation and stabilization by SENP1 result in promoted cyclin D1 and vascular endothelial growth factor (VEGF) levels, angiogenesis, and cell growth." (PMID 37502217, 2023). "Similar to prostate cancer, our study found that both AR and SENP1 were highly expressed in Xp11.2 tRCC, and the transcript activity of the TFE3 fusion could be regulated by SENP1." (PMID 35452181, 2022). "Therefore, SENP1 is considered to be a promising target for the treatment of HCC and prostate cancer." (PMID 35807394, 2022). "For example, the SUMO1-/sentrin-specific protease SENP1 has a pro-oncogenic role in several types of cancer (including pancreatic ductal adenocarcinoma (PDAC), prostate cancer, hepatocellular carcinoma, and metastatic neuroblastoma tissues), correlating with poor prognosis." (PMID 30349044, 2018). "Moreover, SENP1 overexpression has strong prognostic value in the subset of ERG-positive prostate cancers lacking PTEN deletions." (PMID 26202067, 2015). "However, whether SENP1 participates in TGF-β induced EMT in prostate cancers has not been previously reported." (PMID 28417919, 2017). "Cell-permeable pSI2 effectively inhibited the isopeptidase activity of SENP1, 2, and 3, but not SENP5, resulting in the accumulation of SUMOylated proteins in prostate cancer cells PC-3." (PMID 33923236, 2021). "We previously established that independently either SENP1 Tg or PTEN+/− mouse model develops PIN, but not prostate carcinoma." (PMID 27852060, 2017). "SENP1 immunostaining was slightly more frequent in TMPRSS2:ERG rearranged and ERG positive prostate cancers than in ERG negative tumors." (PMID 26202067, 2015).
breast carcinoma (20 papers, 2011 to 2026). "According to IHC staining, both c‐Myc and SENP1 were upregulated in tumour tissues compared with adjacent healthy tissues and associated with short survival for breast cancer patients." (PMID 38967349, 2024). "Collectively, these findings indicate that the levels of KMT2D and YBX1 are associated with the levels of c‐Myc and SENP1, suggesting a poor prognosis for individuals with breast cancer." (PMID 38967349, 2024). "The rs12297820 variant of SENP1 is associated with metastatic status in breast cancer." (PMID 34503213, 2021). "SENP1 was overexpressed in breast cancer cell lines compared to immortalized mammary epithelia MCF10A cells." (PMID 38389923, 2024). "Accordingly, SENP1 has been shown to promote Pin1-dependent oncogenesis, and SENP1 and Pin1 expression levels are positively correlated in breast cancer tissue." (PMID 38745861, 2024). "KMT2D‐mediated H3K4me1 mark and YBX1 were colocalized at the TSS and promoter regions of the c‐Myc and SENP1 genes in breast cancer cells." (PMID 38967349, 2024). "In breast cancer, suppression of SENP1 activity diminishes deSUMOylation of HIF‐1α, culminating in HIF‐1α degradation and inhibition of cancer metastasis." (PMID 39205481, 2024). "In breast cancer, SENP1 inhibition prevents the deSUMOylation of hypoxia-inducible factor 1α (HIF-1α), ultimately leading to HIF-1α degradation and cancer metastasis suppression." (PMID 38389923, 2024). "For instance, SENP1 and SENP2 genes polymorphisms are associated with different hormone receptor status, lymph node status and tumor grades in breast cancer." (PMID 37684630, 2023). "It is noteworthy that SENP1 was reported to be frequently overexpressed in human breast cancers, resulting in c-Myc stabilization and activation." (PMID 37468105, 2023). "The TCGA breast cancer database showed that there was a significant positive correlation between the expression of β-catenin and SENP1." (PMID 32093760, 2020). "A decrease in SENP1 was also found in CLDN6-overexpressing breast cancer cell lines at both the mRNA and protein levels." (PMID 32093760, 2020). "Overexpression of SENP1 has been observed in several cancer types, including colon cancer, proteases cancer, and breast cancer." (PMID 31969492, 2020). "Our study for the first time showed a link between the variability of SENP1 gene and metastasis in breast cancer." (PMID 27178176, 2016). "The aim of these studies was to investigate an association between polymorphic variants (SNPs) of the SENP1 gene (c.1691 + 36C > T, rs12297820) and SENP2 gene (c.902C > A, p.Thr301Lys, rs6762208) and a risk of breast cancer occurrence." (PMID 27178176, 2016). "This fact prompted us to investigate the correlation between polymorphic variants (SNPs) of the SENP1 gene (c.1691 + 36C > T, rs12297820) and SENP2 gene (c.902C > A, p.Thr301Lys, rs6762208) and breast cancer risk." (PMID 27178176, 2016). "Furthermore, SENP1 was reported to enhance PIN1 activity via deSUMOylation in breast cancer, suggesting a potential regulatory axis involving SENP1, PIN1, and the HBx protein in HCC that remains to be elucidated." (PMID 41438340, 2026). "SENP1-mediated deSUMOylation enhances PIN1 activity in breast cancer." (PMID 41438340, 2026). "Research had indicated that inhibiting SENP1 in breast cancer, hepatocellular carcinoma and prostate cancer could impact their proliferation, invasion and migration, and also plays an important role in brain injury, heart injury, lung injury, liver injury." (PMID 39205481, 2024). "As a result, the KMT2D‐H3K4me1‐YBX1 axis may facilitate breast cancer progression by positively modulating the expressions of c‐Myc and SENP1." (PMID 38967349, 2024). "Considering that SENP1 also overexpressed in breast cancer, Triptolide may potentially be used for the treatment of breast cancer." (PMID 35216622, 2022). "Thus, we propose that CLDN6 plays an anti-metastatic role in breast cancer by antagonizing the SENP1/HIF-1α signalling pathway." (PMID 32093760, 2020).
breast carcinoma (continued). "Because CLDN6 attenuates hypoxia-induced tumour metastasis in a SUMOylation-dependent manner, these findings might provide a novel strategy for breast cancer treatment, and directly targeting SENP1/HIF-1α might prove to be a beneficial anti-cancer therapy." (PMID 32093760, 2020). "Because K391 and K477 SUMO sites are required for SENP1-regulated HIF-1α deSUMOylation, we wondered whether mutations in the SUMO site in HIF-1α would prevent the effect of CLDN6 overexpression in breast cancer cells." (PMID 32093760, 2020). "We also studied an association between the polymorphisms of the SENP1 and SENP2 genes and clinical characteristics of breast cancer patients such as lymph node status, tumor grade, hormone receptors (estrogen and progesterone receptors) and epidermal growth factor receptor (HER2) expression." (PMID 27178176, 2016). "Furthermore, SENP1 can deSUMOylate and regulate the protein activity and oncogenic function of the isomerase Pin1, which is an important regulator of cellular processes involving Pro-directed phosphorylation in breast cancer." (PMID 33968766, 2021). "Consistently, mammary tumour tissues from both MMTV‐KMT2D‐KD and MMTV‐YBX1‐KD mice showed decreased expression levels of SENP1, c‐Myc and Ki67." (PMID 38967349, 2024). "The results indicate that SENP1 downregulation blocks epithelial-mesenchymal transition (EMT) process and thus inhibits breast cancer cell invasion and metastasis, which is mediated via ZEB1 expression." (PMID 35342335, 2022). "For example, a study found that SENP1 can deSUMOylate HIF-1α to enhance HIF-1α stabilization and ultimately promote breast cancer metastasis." (PMID 33968766, 2021). "The reduction in SENP1 promotes the SUMOylation of HIF-1α, which decreases the stability and transcriptional activity of HIF-1α, thus contributing to the inhibition of breast cancer metastasis." (PMID 32093760, 2020). "This process reduced SENP1 expression and prevented the deSUMOylation of HIF-1α, ultimately leading to HIF-1α degradation and breast cancer metastasis suppression." (PMID 32093760, 2020). "Gene expression data from a breast cancer microarray were acquired from the GEO database (GSE27562), and a GSEA was performed for SENP1 and CLDN6 expression." (PMID 32093760, 2020). "Consistently, the overexpression of SENP1 or HIF-1α significantly restored the CLDN6-mediated reductions in circulating tumour cells, indicating that CLDN6 inhibits breast cancer metastasis through SENP1/HIF-1α signalling in vivo." (PMID 32093760, 2020). "A Pearson correlation analysis demonstrated that CLDN6 expression was negatively correlated with SENP1 and HIF-1α in breast cancer tissues." (PMID 32093760, 2020). "Furthermore, the levels of SENP1 and c‐Myc showed a positive correlation with KMT2D and YBX1 in the breast cancer tissues analyzed as well as 17 TNBC tissues in this cohort." (PMID 38967349, 2024). "Another prospective study is evaluating the expression levels of SENP1 in bone metastatic and non-metastatic mammary carcinomas to determine its potential use as a therapeutic target and prognostic marker in breast cancer (NCT04167605)." (PMID 34503213, 2021). "In our study, CLDN6 appears to be able to regulate the HIF-1 pathway through SENP1 not only in breast cancer cell lines but also in non-tumorigenic HBL-100 cell lines." (PMID 32093760, 2020). "In PR-A positive breast cancer cells, co-transfection of SENP1 but not mSENP1 also enhances transcription demonstrating that this effect is not cell specific (not shown)." (PMID 29301281, 2018). "Our results suggest that the variability of the SENP1 and SENP2 genes may play a role in breast cancer occurrence." (PMID 27178176, 2016). "Furthermore, the genetic variability of SENP1 and SENP2 may play a role in the occurrence of breast cancer." (PMID 34503213, 2021). "The variability of the SENP1 and SENP2 genes may play a role in breast cancer occurrence." (PMID 27178176, 2016).
hepatocellular carcinoma (20 papers, 2018 to 2026). A malignant tumor that arises from hepatocytes. "Firstly, we detected the expression level of RHOU, AnxA6 and SENP1 protein in mouse orthotopic hepatoma tissues." (PMID 38566133, 2024). "In hepatocellular carcinoma cells, SENP1 induces stemness-related genes expression such as Oct3/4, Nanog, NOTCH1 and BMI-1 through enhancing the stability and transcriptional activity of HIF-1α, ultimately leading to cancer cell self-renewal." (PMID 38389923, 2024). "The expression of SENP1 is dramatically increases in multidrug-resistant hepatocellular carcinoma cells." (PMID 38389923, 2024). "The study in hepatocellular carcinoma demonstrated that SENP1 deletion inhibited proliferation and induced cell cycle dysregulation through the deSUMOylation of ubiquitin conjugating enzyme E2 T (UBE2T)." (PMID 38389923, 2024). "SENP1 increases the sphere formation ability of hepatocellular carcinoma cells through deSUMOylating HIF-1α." (PMID 38389923, 2024). "In hepatocellular carcinoma, SENP1 knockdown suppresses EMT by increasing the expression of E-cadherin and zonula occludens-1 (ZO-1) while decreasing fibronectin and N-cadherin." (PMID 38389923, 2024). "In hepatocellular carcinoma (HCC), UBE2T desumoylation by SENP1 is related to carcinogenesis, which associates with upregulation of both proteins." (PMID 35887358, 2022). "For example, SENP1 deletion destroyed carcinoma cells’ growth, migration and invasion, and enhanced its apoptosis in hepatocellular carcinoma." (PMID 34120412, 2021). "SENP1 regulates hepatocellular carcinoma (HCC) carcinogenesis through deSUMOylation of ubiquitin-conjugating enzyme E2T (UBE2T) and HIF1α." (PMID 34503213, 2021). "Herein, we revealed enhanced SENP1 expression in most hepatocellular carcinoma tissues as compared with their adjacent normal tissues." (PMID 31969492, 2020). "Most hepatoma cell lines showed fairly high expression level of SENP1, including Chang liver, SNU-423, SMMC-7721, LM3, 97H and HepG2." (PMID 31969492, 2020). "In their study, SENP1 was stably expressed in hepatoma cells, while the expression level of SENP3 decreased, suggesting the possibility of negative feedback regulation of SENP3, which was consistent with the hypothesis in the present study." (PMID 36840491, 2023). "SENP1 can be utilized as a molecular target in the discovery of anti-tumor drugs vs. human hepatocellular carcinoma (HCC) metastasis." (PMID 34276383, 2021). "lncRNA FRMD6-AS1 is significantly upregulated in hepatocellular carcinoma tissues and cells, regulating the stability of HIF-1α through direct interaction with the de-SUMOylating enzyme SENP1." (PMID 40861273, 2025). "SENP1 might be utilized as a molecular target for the discovery of antitumor drugs vs. human hepatocellular carcinoma (HCC) metastasis." (PMID 37502217, 2023). "It is known that SENP1 regulates the migration and epithelial-mesenchymal transition (EMT) of hepatocellular carcinoma." (PMID 33534099, 2021). "The protein level of SENP1 was examined in hepatocyte line (LO2) and hepatoma cell lines (Bel-7402, QGY-7701, Chang liver, SNU-423, SMMC-7721, LM3, 97L, 97H, HepG2)." (PMID 31969492, 2020). "Herein, our findings showed that both SENP1 and UBE2T were upregulated in either hepatoma cell lines or tumor tissues and their expression levels were positively related." (PMID 31969492, 2020). "More recent studies are in agreement with these results, reporting that SENP1 increased the stabilization and transcriptional activity of HIF-1α in hypoxia via desumoylation in hepatocellular carcinoma (HCC) and ovarian cancer cells." (PMID 33114748, 2020). "The cooperative roles of SENP1 and UBE2T in development and progression of hepatocellular carcinoma (HCC) are still unknown." (PMID 31969492, 2020). "The positive feedback between SENP1 and HIF-1α can improve the stem cell characteristics of hepatocellular carcinoma (HCC) and promote the occurrence of HCC." (PMID 33791211, 2021).